RPL24P4 (RPL24 pseudogene 4)
Synonyms: dJ125M3.1; RPL24_1_692
Gene: Processed pseudogene on chromosome 6 (42,956,345 to 42,956,765, reverse strand). Ensembl gene ENSG00000181524.
Diseases named in the same sentence as RPL24P4 in open-access papers:
RPL24P4 is named in the same sentence as 2 diseases in open-access papers, as found by Europe PMC text mining. Sharing a sentence is not in itself a finding about the gene and the disease.
RPL24P4 shares sentences with these, for which no sentence is quoted: dengue (1 paper); hereditary hypotrichosis simplex (1).